USP13 (ubiquitin specific peptidase 13)
Diseases named in the same sentence as USP13 in open-access papers (continued):
Sharing a sentence is not in itself a finding about the gene and the disease.
cholangiocarcinoma (8 papers, 2021 to 2023). A carcinoma that arises from the intrahepatic biliary tree (intrahepatic cholangiocarcinoma) or from the junction, or adjacent to the junction, of the right and left hepatic ducts (hilar cholangiocarcinoma). "Recently, it has been reported that USP13-mediated deubiquitination is associated with MYC in cholangiocarcinoma, glioma stem cells, and hepatocellular carcinoma." (PMID 38093367, 2023). "CLK3-mediated phosphorylation of USP13 at Tyr708 promotes cholangiocarcinoma progression by activating c-Myc-induced purine synthesis, providing a new and viable therapeutic target for treating cholangiocarcinoma associated with CLK3 mutations." (PMID 36612196, 2022). "Moreover, a recent study also found that CDC-like kinase 3 (CLK3) or the cholangiocarcinoma-associated CLK3-Q607R mutant can directly phosphorylate USP13 at Tyr708, and promote its binding to c-Myc." (PMID 34177595, 2021). "Thus, CLK3-mediated phosphorylation of USP13 at Tyr708 promotes cholangiocarcinoma progression by activating c-Myc-induced purine synthesis, providing a new and viable therapeutic target for the treatment of cholangiocarcinoma associated with CLK3 mutations." (PMID 34177595, 2021). "CLK3 activates the c‐Myc‐mediated transcription of purine metabolic genes by phosphorylating USP13 at Y708 in cholangiocarcinoma." (PMID 35092699, 2022). "Furthermore, CLK3-induced phosphorylation of the Tyr708 residue in USP13 promotes cholangiocarcinoma progression by activating c-Myc-mediated purine synthesis." (PMID 34177595, 2021). "In research on nucleotide anabolism in cholangiocarcinoma, CDC like kinase 3 (CLK3) was found to activate the rate-limiting enzyme in de novo purine anabolism, ATIC, by regulating the USP13/Fbxl14/c-Myc signaling axis, thereby promoting the molecular progression of cholangiocarcinoma." (PMID 33952722, 2021). "Recently, it has been reported that USP13 is co-overexpressed with c-Myc in many tumors, such as NSCLC, cholangiocarcinoma (CAA), GSCs, and hepatocellular carcinoma (HCC)." (PMID 35445009, 2022).
lung carcinoma (8 papers, 2018 to 2025). "Here, we developed and employed a novel GEMM to elucidate the role of USP13 in lung cancer development." (PMID 38093367, 2023). "We showed a strong molecular association between USP13 and c-MYC, leading to the upregulation of squamous programs in murine and human lung cancer cells." (PMID 38093367, 2023). "USP13 gene is amplified in human lung cancer and clinical samples of non-small cell lung cancer (NSCLC) showed tumor exhibited high USP13 level compared with adjacent normal tissues." (PMID 35898882, 2022). "USP13 is significantly amplified in over 20% of lung cancer patients and critical for tumor progression." (PMID 35898882, 2022). "Future studies are warranted to determine how USP13 reprograms lineage plasticity in USP13-amplified lung cancers and whether targeting USP13 can overcome therapeutic-resistant LUSC-transformed lung tumors." (PMID 38093367, 2023). "Similarly, IHC assessment of a lung cancer tissue microarray showed that USP13 and MCL1 were upregulated in cancers compared with the matched adjacent normal tissues, and their expression tended to correlate (Spearman’s rank correlation coefficient R = 0.46, P = 0.13)." (PMID 29335437, 2018). "Specifically, USP13 and MCL1 expression was both observed in 93.3% (28 of 30) of our lung cancer cohort, whereas only 26.7% (8 of 30) and 3.3% (1 of 30) of normal lung tissues displayed positive staining of USP13 and MCL1, respectively." (PMID 29335437, 2018). "USP13 is one of the most amplified genes in LUSC, yet its role in lung cancer is largely unknown." (PMID 38093367, 2023).
hepatocellular carcinoma (7 papers, 2020 to 2025). A malignant tumor that arises from hepatocytes. "Overall, this research reveals that hypoxia-induced USP13 expression drives ferroptosis resistance and tumor immune evasion in hepatocellular carcinoma through the stabilization of ACLY." (PMID 41330897, 2025). "Correlation between USP13 expression and clinicopathologic characteristics of patients with hepatocellular carcinoma." (PMID 33195243, 2020). "However, the precise mechanisms by which USP13 influences hepatocellular carcinoma (HCC) cell proliferation remain to be fully elucidated." (PMID 40208227, 2025). "Additionally, increased USP13 expression was observed in hepatic hepatocellular carcinoma (HCC) and high level of USP13 was correlated with larger tumor size, advanced tumor-node-metastasis (TNM) stage, and lower overall survival." (PMID 36188217, 2022).
cervical cancer (6 papers, 2021 to 2025). A primary or metastatic malignant neoplasm involving the cervix. "Depletion of USP13 using a pool of specific siRNAs caused a significant reduction in HPV + cervical cancer cell growth." (PMID 33627786, 2021). "USP13 has been found to be highly expressed in various tumors, including lung, kidney, and cervical cancers." (PMID 41330897, 2025). "Another study has shown that USP13 is essential for HPV-positive cervical cancer cells to proliferate, at least in part by deubiquitinating and stabilizing the prosurvival protein Mcl-1." (PMID 35804810, 2022). "Our data demonstrate that inhibition of USP13 with Spautin-1 reduces Mcl-1 expression and sensitises cervical cancer cells to the BH3 mimetic ABT-263, offering a potential therapeutic strategy for cervical cancer." (PMID 33627786, 2021). "Our cell line data showed higher USP13 expression in HPV + cervical cancer cells compared to normal control cells." (PMID 33627786, 2021). "Mcl-1 protein levels were significantly higher in cervical cancer cells when compared to NHKs and correlated with increased USP13 expression in the cervical cancer cell lines (R = 0.862, p = 0.015)." (PMID 33627786, 2021). "By examining the copy number alterations (CNAs) of DUB genes in the human genome using a previously curated gene list we observed amplification of USP13 in approximately 15% of cervical cancers, which was also seen in a number of other squamous carcinomas." (PMID 33627786, 2021). "Collectively, these findings demonstrate that USP13 and Mcl-1 are concomitantly over expressed in cervical cancer tissue, suggesting that the regulation of Mcl-1 by USP13 is clinically relevant." (PMID 33627786, 2021). "To confirm the increased USP13 protein expression in cervical cancer, we performed immunohistochemistry (IHC) on a cervical cancer tissue microarray (TMA)." (PMID 33627786, 2021). "We further demonstrated that USP13 was required for the proliferation of HPV positive cervical cancer cells, at least in part via the deubiquitination and stabilisation of the pro-survival protein, Mcl-1." (PMID 33627786, 2021). "In line with the data from cell lines, USP13 protein expression was significantly higher in the cervical cancer tissue." (PMID 33627786, 2021). "To investigate if targeting USP13 to reduce Mcl-1 expression has therapeutic potential in cervical cancer, we first assessed the impact of USP13 inhibition by the small molecule inhibitor Spautin-1." (PMID 33627786, 2021). "In contrast, depletion of USP13 had minimal impact on cell proliferation or colony formation in HPV- cervical cancer cells." (PMID 33627786, 2021). "We also demonstrate that pharmacological inhibition of USP13 sensitises cervical cancer cells to a BH3 mimetic inhibitor by reducing Mcl-1 protein expression, inducing cell death." (PMID 33627786, 2021). "Immunoprecipitation with either antibody resulted in the detection of both USP13 and Mcl-1, suggesting that the endogenous proteins interact in cervical cancer cells." (PMID 33627786, 2021). "Taken together, JNK-dependent c-Jun activation is necessary for USP13 expression in cervical cancer cells." (PMID 33627786, 2021). "Together, these results show that expression of catalytically active USP13 is required for the proliferation of HPV + cervical cancer cells." (PMID 33627786, 2021). "As USP13 depletion resulted in the inhibition of cell proliferation in cervical cancer cells, we investigated if this was due to the reduction in Mcl-1 levels." (PMID 33627786, 2021). "We therefore investigated if pharmacological inhibition of USP13 using Spautin-1 sensitised cervical cancer cells to ABT-263." (PMID 33627786, 2021). "In contrast, we have taken a more holistic approach and assessed the role of USP13 in Mcl-1 stabilisation with a range of complementary assays, providing robust evidence that USP13 can indeed regulate Mcl-1 expression in cervical cancer cells." (PMID 33627786, 2021).
cervical cancer (continued). "Together, our data demonstrates that USP13 is a potential oncogene in cervical cancer that functions to stabilise the pro-survival protein Mcl-1, offering a potential therapeutic target for these cancers." (PMID 33627786, 2021). "To confirm the clinical relevance of the USP13 – Mcl-1 interaction, we first analysed the expression of Mcl-1 in our panel of cervical cancer cells." (PMID 33627786, 2021). "We confirmed that USP13 expression was increased in cervical cancer cell lines, cytology samples from patients with cervical disease and in cervical cancer tissue." (PMID 33627786, 2021). "In conclusion, we have identified that the DUB USP13 is a potential oncogene in cervical cancer that promotes proliferation by deubiquitinating and stabilising the pro-survival protein Mcl-1." (PMID 33627786, 2021). "To confirm our experimental studies, we analysed USP13 expression in the TCGA cervical cancer dataset based on HPV status." (PMID 33627786, 2021). "Mcl-1 is a pro-survival protein that is often associated with resistance to BH3 mimetic treatment; this study demonstrated that the depletion or inhibition of USP13 sensitises HPV+ cervical cancer cells to BH3-mimetics, a potential therapeutic approach in these cancers." (PMID 40011575, 2025). "Taken together, these data suggest that USP13 mediated stabilisation of Mcl-1 may be a potential mechanism for the resistance of cervical cancer cells to BH3 mimetics." (PMID 33627786, 2021). "Importantly, expression of Mcl-1 significantly correlated with USP13 expression in cervical cancer tissue from the same patient (R = 0.4128, p = 0.009)." (PMID 33627786, 2021). "This suggests that additional USP13 substrates may contribute to cervical cancer cell proliferation." (PMID 33627786, 2021). "Depletion of USP13 inhibited cervical cancer cell proliferation." (PMID 33627786, 2021). "We identified that USP13 is the most amplified DUB gene in cervical cancer." (PMID 33627786, 2021). "We therefore wished to further investigate how USP13 expression is regulated in cervical cancer." (PMID 33627786, 2021). "To investigate if USP13 expression may contribute to the development of cervical cancer, we analysed USP13 mRNA expression in cervical cytology samples from a cohort of HPV16 + patients." (PMID 33627786, 2021). "Next, we examined the expression of USP13 in a panel of cervical cancer cell lines." (PMID 33627786, 2021). "We identified that USP13 is amplified in about 15% of cervical cancer cases." (PMID 33627786, 2021). "Importantly, USP13 copy number positively correlated with USP13 mRNA expression in cervical cancer (R = 0.350)." (PMID 33627786, 2021). "Finally, we confirmed that depletion of USP13 from both HeLa and SiHa cells increased the ubiquitination of endogenous Mcl-1, suggesting USP13-mediated deubiquitination of Mcl-1 is relevant in cervical cancer cells." (PMID 33627786, 2021). "Interestingly, restoration of Mcl-1 expression only partially restored cell proliferation in USP13 depleted cervical cancer cells." (PMID 33627786, 2021). "We therefore investigated how USP13 expression was regulated in cervical cancer cells." (PMID 33627786, 2021). "Finally, we demonstrated that depletion of USP13 expression or inhibition of USP13 enzymatic activity increased the sensitivity of cervical cancer cells to the BH3 mimetic inhibitor ABT-263." (PMID 33627786, 2021). "Importantly, the pharmacological inhibition of USP13 sensitizes HPV-positive cervical cancer cells to BH3 mimetic inhibitors, implying that targeting USP13 could be beneficial in the treatment of these tumors." (PMID 35804810, 2022). "In addition, the TCGA cervical cancer database shows minimal mutations in the USP13 gene (data not shown)." (PMID 33627786, 2021). "Importantly, the expression of USP13 and Mcl-1 proteins correlated in cervical cancer tissue." (PMID 33627786, 2021).
cervical cancer (continued). "Therefore, we suggest that targeting USP13 may offer a therapeutic benefit in cervical cancer patients via the reduction in Mcl-1 protein expression." (PMID 33627786, 2021). "In validation of our data in cervical cancer cell lines and cervical cancer tissue, USP13 mRNA expression was also significantly upregulated in several published microarray databases, suggesting that increased USP13 expression is a common occurrence in cervical cancer." (PMID 33627786, 2021). "USP13, which is sits on chromosome 3q26 that is highly amplified in cervical cancer, plays a key role in regulating Mcl-1 expression in HPV+ cervical cancer cells." (PMID 40011575, 2025). "USP13 is localized adjacent to PIK3CA in the 3q26.3 locus, which is frequently amplified in human cancers such as brain, lung, ovarian, esophageal and cervical cancers, and high USP13 expression is correlated with poor survival outcomes." (PMID 36385557, 2022). "In contrast, USP13 protein levels were increased in both HPV + and HPV- cervical cancer cells compared to NHKs, when analysed by western blot." (PMID 33627786, 2021). "By interrogating the cervical cancer data from the TCGA consortium, we noted that the DUB USP13 is amplified in ~15% of cervical cancer cases." (PMID 33627786, 2021). "The cervical cancer TCGA dataset demonstrates that 8% of cervical cancers have high USP13 mRNA expression in the absence of USP13 copy number amplification." (PMID 33627786, 2021). "Crucially, we demonstrated that pharmacological inhibition of USP13 sensitises HPV positive cervical cancer cells to BH3 mimetic inhibitors, suggesting that the targeting of USP13 may have therapeutic benefit in these cancers." (PMID 33627786, 2021). "Furthermore, whilst our data demonstrates that USP13 plays a role in regulating cervical cancer cell proliferation via the stabilisation of Mcl-1, it is clear that several other DUBs play complimentary roles in regulating Mcl-1 expression that may also play pro-oncogenic roles in cervical cancer." (PMID 33627786, 2021). "In addition to the USP13 amplification observed by our analysis of the TCGA cervical cancer dataset, we noted that several cases had high USP13 mRNA expression in the absence of USP13 amplification." (PMID 33627786, 2021). "In agreement with our cell line data, USP13 expression was not significantly different between HPV + and HPV- cervical cancer." (PMID 33627786, 2021). "When compared to primary normal human keratinocytes (NHKs), USP13 mRNA expression was higher in HPV positive (HPV + ), but not HPV negative (HPV-) cervical cancer cells." (PMID 33627786, 2021).
prostate carcinoma (6 papers, 2019 to 2026). A carcinoma that arises from epithelial cells of the prostate gland. "This study aimed to evaluate the relationship between USP13 immunohistochemical staining intensity and clinicopathological factors associated with prostate cancer progression." (PMID 42195268, 2026). "Clinically, USP13 was significantly up-regulated in prostate cancer tissues and positively associated with PCMT1 expression." (PMID 42056074, 2026). "In the current study, we investigated the prognostic role of USP13 in prostate cancer and explored the underlying biological functions of USP13 in driving PCa progression." (PMID 36564767, 2022). "The clinicopathological characteristics and USP13 expression of 499 patients with prostate cancer were obtained from TCGA, and the association of USP13 expression and clinicopathological characteristics was analyzed using the chi-square test and Fisher’s exact test." (PMID 36564767, 2022). "Our studies demonstrate that inhibition of USP13 can offer a viable therapeutic option to overcome enzalutamide resistance in prostate cancer patients with USP13/PCMT1-overexpression." (PMID 42056074, 2026). "Here, we reveal that the deubiquitinating enzyme USP13 is up-regulated in PCa tissues and correlates with prostate cancer progression." (PMID 42056074, 2026). "Expression of USP13 in single cell types separated from prostate cancer tumors was measured by analyzing the single cell RNA sequencing (scRNA-seq) data in GEO database." (PMID 36564767, 2022). "Next, we analyzed USP13 expression and its prognostic value in prostate cancer based on the TCGA database and GTEx database." (PMID 36564767, 2022). "Second, the size of our cohort included in this study was too small, a large cohort of patients with clinical tissue specimens was needed to make a better statistical analysis regarding the clinical significance of USP13 in prostate cancer." (PMID 36564767, 2022). "Taken together, the analysis of pathway and process enrichment and PPI enrichment further confirmed the carcinogenesis and immune-related signatures of USP13 in prostate cancer." (PMID 36564767, 2022). "Through the present study, we concluded that USP13 potentially modulates the tumor microenvironment of prostate cancer through multiple mechanisms." (PMID 36564767, 2022). "Third, although we tried to identify the prognostic value of USP13 gene in prostate cancer, the results were mostly basing on gene expression of USP13 in PCa samples." (PMID 36564767, 2022). "Our study indicated a potential mechanism through which USP13 gene expression was regulated in prostate cancer, although the ceRNA network needs to be further validated in cell line and animal models." (PMID 36564767, 2022). "Nonetheless, to date, little is known about the biological function and immunity-related mechanisms of USP13 in prostate cancer." (PMID 36564767, 2022). "USP13 silencing inhibits prostate cancer cell growth in vitro and in vivo." (PMID 42056074, 2026). "(C) Heatmaps showing the top 50 genes negatively correlated with USP13 in prostate cancer." (PMID 36564767, 2022). "To conclude, our study uncovered the prognostic value and carcinogenic role of USP13 in prostate cancer and showed that overexpression of USP13 may lead to activation of cancer-driving signaling pathways, such as PI3k, Wnt and AR." (PMID 36564767, 2022). "(B) Heatmaps showing the top 50 genes positively correlated with USP13 in prostate cancer." (PMID 36564767, 2022). "The ectopic expression of USP11 in PTEN-proficient human prostate cancer cell line DU145 depleted of USP13 or OTUD3 still upregulated PTEN, suggesting that USP11 could be a more potent regulator of PTEN than other DUBs in our assays." (PMID 30733438, 2019). "In addition, USP13 was found to be enriched in the hypoxia response via HIF activation, suggesting that targeting USP13 may suppress hypoxia and thereby promote immune infiltration and the response to immunotherapy in prostate cancer." (PMID 36564767, 2022).